CMPK2 (cytidine/uridine monophosphate kinase 2)
Description:
Mitochondrial nucleotide monophosphate kinase needed for salvage dNTP synthesis that mediates immunomodulatory and antiviral activities through IFN-dependent and IFN-independent pathways. Restricts the replication of multiple viruses including flaviviruses or coronaviruses. Together with viperin/RSAD2 and ddhCTP, suppresses the replication of several coronaviruses through inhibition of the viral RNA-dependent RNA polymerase activities. Concerning flaviviruses, restricts RNA translation when localized to the mitochondria independently of its kinase activity. Is able to phosphorylate dUMP, dCMP, CMP, UMP and monophosphates of the pyrimidine nucleoside analogs ddC, dFdC, araC, BVDU and FdUrd with ATP as phosphate donor. Efficacy is highest for dUMP followed by dCMP while CMP and UMP are poor substrates. Controls therefore mitochondrial DNA synthesis by supplying required deoxyribonucleotides (By similarity). CMPK2-dependent mitochondrial DNA synthesis is necessary for the production of oxidized mitochondrial DNA fragments after exposure to NLRP3 activators (By similarity). In turn, cytosolic oxidized mtDNA associates with the NLRP3 inflammasome complex and is required for its activation (By similarity).
Synonyms: TYKi; UMP-CMPK2; NDK; IBGC10; TMPK2
Tractability: PROTAC: ubiquitination databases record sites on it; its protein half-life has been measured.
Gene: Protein-coding gene on chromosome 2 (6,840,570 to 6,866,635, reverse strand). Ensembl gene ENSG00000134326.
Subcellular location: Mitochondrion
Subcellular location (Human Protein Atlas): Mitochondria; Nucleoplasm
Gene Ontology:
Molecular function: nucleoside diphosphate kinase activity; UMP kinase activity; deoxynucleoside phosphate kinase activity, ATP as phosphate donor; CMP kinase activity; dCMP kinase activity; dTMP kinase activity; dUMP kinase activity; nucleoside monophosphate kinase activity
Biological process: dTDP biosynthetic process; dTTP biosynthetic process; dUDP biosynthetic process
Cellular component: mitochondrion
Genetic constraint (gnomAD): Loss-of-function variants: 30 observed, 23.65 expected, observed/expected ratio (o/e) 1.27, 90% interval 0.95 to 1.71. The synonymous counts are far from expectation, so gnomAD's model fits this gene poorly and the ratio says little. Missense variants: 669 observed, 507.4 expected, observed/expected ratio (o/e) 1.32, 90% interval 1.24 to 1.4. Synonymous variants: 299 observed, 214.5 expected, observed/expected ratio (o/e) 1.39, 90% interval 1.27 to 1.53.
Homologues: Orthologues: chimpanzee CMPK2 (99% identical), macaque CMPK2 (95% identical), rabbit CMPK2 (79% identical), pig CMPK2 (76% identical), mouse Cmpk2 (74% identical), rat Cmpk2 (72% identical), guinea pig CMPK2 (72% identical), dog CMPK2 (71% identical), tropical clawed frog cmpk2 (42% identical), zebrafish cmpk2 (38% identical), Caenorhabditis elegans dtmk-1 (11% identical). Paralogues in human: DTYMK (10% identical).
Diseases named in the same sentence as CMPK2 in open-access papers:
CMPK2 is named in the same sentence as 43 diseases in open-access papers, as found by Europe PMC text mining. Sharing a sentence is not in itself a finding about the gene and the disease. The quoted sentences say what the papers report.
viral infections (21 papers, 2014 to 2025). "Collectively, our results implicate CMPK2 as an effective host defense factor during virus infection and provided a novel cellular target for controlling CoV infections." (PMID 36930652, 2023). "In the present study, we found that the CMPK2 mRNA levels increased after poly(I:C) stimulation as well as upon virus infection, which was consistent with the increase of IFN-β levels." (PMID 35633731, 2022). "In a subset of patients for whom RNA-seq data were available, we showed that viperin and CMPK2 expression was also increased in patients with viral infections." (PMID 35128501, 2022). "In term of virus infection, human CMPK2 was significantly increased after the infection of viruses, such as Hepatitis E virus (HEV) and Porcine reproductive and respiratory syndrome (PRRS) virus." (PMID 35633731, 2022). "The expression of CMPK2 is up-regulated during various viral infections, implicating that VIPERIN and CMPK2 are functionally connected." (PMID 32983049, 2020). "Further work must be done on the connection between viral infections and the altered essentiality of CMPK2." (PMID 32362913, 2020). "Carp cytidine monophosphate kinase 2 (CMPK2) is upregulated by bacterial challenge and has a protective effect on the gut barrier, suggesting that teleost CMPK2 is involved in innate immune responses against bacterial and viral infections." (PMID 38803570, 2024). "Currently, efforts are being made to identify and characterize host and viral factors that may interact with CMPK2, particularly the N-terminal domain, during viral infection and to elucidate whether such factors regulate its antiviral activity." (PMID 37075076, 2023). "In the upregulated genes in both chMDA5 and poly(I:C) groups, many genes were ISGs, such as MX1, IFI6, IFIT5, RSAD2, OASL, and, CMPK2, which suggested that these genes might play important roles in restricting virus infection in chicken." (PMID 32183248, 2020). "The findings suggest that CMPK2 is connected to the cellular response to a viral infection." (PMID 32362913, 2020). "In order to figure out whether mRNAs and miRNAs in the ceRNA network have effects on viral infection, we investigated the effect of selected six representative mRNAs (CMPK2, ISG15, PARP10, SAMD9, GBP1, and RIG-I) involved in the ceRNA network upon HTNV infection." (PMID 32232013, 2020). "Intriguingly, CMPK2 and Viperin are often coexpressed after IFN-I stimulation or viral infection." (PMID 36930652, 2023). "Interestingly, we also detected high expression levels of antibacterial genes (SAA, CHTA−2B, CMPK2, CD209, LECT2, and NK−lysin) by RNA−seq, suggesting that viral infection disrupts the microbial balance of the gut." (PMID 36016461, 2022). "The induction kinetics presented in this study suggests that CMPK2 may be induced through the LPS and Poly (I:C) mediated IRF3-type I IFN signaling pathway and is involved in the immune response against both bacterial and viral infections." (PMID 34705862, 2021). "Secondly, when investigating the co-expression cluster that CMPK2 belongs to (cluster 42) and performing enrichment analysis on the 90 included genes, both obtained GO BP terms and enriched KEGG pathways are exclusively related to virus infection and cellular defense response." (PMID 32362913, 2020). "Interestingly, only minor to moderate reduction in the induction of IRF7, IRF1, VIPERIN, IFIT5, and CMPK2 was observed at 24 hpi, probably reflecting the involvement of IFN-independent mechanisms in regulating the induction of these genes at late stages of the viral infection cycle." (PMID 35891486, 2022). "Notably, we discovered upregulation of multiple ISGs, such as ZBTB16, MX1, OASL, RSAD2, CMPK2, and CXCL14 in the DiMNF treated primary cells, even in the absence of viral infection." (PMID 37672505, 2023).
viral infections (continued). "In particular, 8 genes (Mx1, EPSTI1, XAF1, IFI44L, GBP1, SAMD9, SAMD9L, and CMPK2) were expressed in the highly resistant cell lines HPAF-II and Hs766T but not the highly permissive cell lines MIA PaCa-2 and Capan-1 in the absence of virus infection." (PMID 27533247, 2016).
COVID-19 (6 papers, 2022 to 2025). A disease caused by infection with severe acute respiratory syndrome coronavirus 2. "In COVID-19 studies, CMPK2 was highly upregulated in severe cases related to ARDS." (PMID 35625619, 2022). "Additionally, CMPK2, which is upregulated in COVID-19 patients’ leukocytes, may play key roles in antiviral immunity and has been positioned as a therapeutic target against SARS-CoV-2 and other RNA viruses." (PMID 39945535, 2025). "CMPK2 (Cytidine/uridine monophosphate kinase 2) is a thymidylate kinase, known to be associated with mitochondrial DNA (mtDNA) synthesis, and may attenuate the severity of acute respiratory distress syndrome (ARDS), a common complication of severe COVID-19, by rate-limiting for mtDNA synthesis." (PMID 35958619, 2022).
atherosclerosis (3 papers, 2021 to 2022). A disease characterized by the build-up of fatty material and calcium deposition in the arterial wall resulting in partial or complete occlusion of the arterial lumen. "Second, CMPK2 may localize in mitochondria and is associated the differentiation of macrophages, a major cell population involved in atherosclerosis processes." (PMID 33874983, 2021). "CMPK2 (cytidine/uridine monophosphate kinase 2) is localized in the mitochondria, where it engages in macrophage differentiation that is involved in atherosclerosis processes." (PMID 35955709, 2022). "Nevertheless, experiments using siRNA or CRISPR/Cas9 approaches to knockdown or knockout CMPK2, respectively, confirmed the roles of CMPK2 in IFN-α-mediated foam cell formation and atherosclerosis-associated events." (PMID 33874983, 2021). "Accordingly, this study examined the potential impact of IFN-α on foam cell formation and atherosclerosis-related effects and the roles of CMPK2 in IFN-α-mediated pro-atherogenic effects." (PMID 33874983, 2021). "Although oxLDL uptake via SR-A induces the transformation of macrophages into foam cells, which is a key precursor to atherosclerosis, we found that CMPK2 is critical for IFN-α-enhanced foam cell formation because, at a minimum, it regulates SR-A expression." (PMID 33874983, 2021). "It is anticipated that the results from more solid approaches examining CMPK2-KO animals will provide supportive and convincing conclusions about the potential role of CMPK2 in exaggerated atherosclerosis in patients with SLE." (PMID 33874983, 2021). "Additional experiments also suggest that CMPK2 might regulate IFN-α-stimulated inflammasome activation, another mechanism associated with atherosclerosis." (PMID 33874983, 2021). "Collectively, our experiments suggest that decreases in SR-A expression and mtROS production, as well as inflammasome pathway inhibition, might be critical effects of CMPK2 in regulating IFN-α-mediated pro-atherosclerosis." (PMID 33874983, 2021). "In addition, CMPK2 was also shown to potentially contribute to premature atherosclerosis in SLE." (PMID 34705862, 2021). "In addition to IFN-α, several triggers of atherosclerosis, including thrombin and IFN-γ, can induce CMPK2 expression, which is elevated in CD4+ T cells and CD14+ monocytes isolated from SLE patients compared to those isolated from controls." (PMID 33874983, 2021). "In addition to IFN-α, several triggers of atherosclerosis, including thrombin and IFN-γ, can induce CMPK2 expression, which was elevated in CD4+ T cells and CD14+ monocytes isolated from SLE patients compared to those isolated from controls." (PMID 33874983, 2021). "In addition to IFN-α, individual treatment with several other atherogenic factors induced CMPK2 expression, suggesting that CMPK2 may play roles in non-IFN-α induced mediation of atherosclerosis." (PMID 33874983, 2021).
colorectal cancer (3 papers, 2021 to 2023). A primary or metastatic malignant neoplasm that affects the colon or rectum. "FUBP3 has been shown to interact with long noncoding RNA CMPK2 and drive colorectal cancer progression via activation of c‐Myc signalling." (PMID 36478132, 2023). "CMPK2—CMPK2 is a long non-coding RNA that is typically upregulated in colorectal cancer and is positively correlated with metastases to lymph nodes and advanced stages through stimulation of FUBP3–c-Myc signaling." (PMID 38304289, 2023). "CMPK2 is a long noncoding RNA that promotes colorectal cancer progression by activating the FUBP3-Myc signaling axis." (PMID 34830961, 2021).
autoimmune disease (2 papers, 2021 to 2022). A disorder resulting from loss of function or tissue destruction of an organ or multiple organs, arising from humoral or cellular immune responses of the individual to their own tissue constituents. "It is remarkable that CD38 may facilitate the development of inflammatory and autoimmune diseases by regulating immune response, and CMPK2 is reported to control NLRP3 inflammasome activation." (PMID 35359935, 2022). "Although further investigation is required, this may indicate that CMPK2 may serve as a reasonable therapeutic target against different autoimmune disorders." (PMID 34705862, 2021). "The information presented in this study could guide future studies on the role of CMPK2 in type -1 IFN dependent anti-viral and anti-bacterial response and may provide a novel potential therapeutic target to the treatment of various type I IFN related autoimmune disorders." (PMID 34705862, 2021).
ZIKV infection (2 papers, 2023 to 2024). "We observed no significant change in ATP production in doxycycline-treated Vero i-EV and i-CMPK2 variant cells upon NanoLuc luciferase reporter ZIKV infection, suggesting that CMPK2-expressing cells are viable." (PMID 37075076, 2023). "Our results showed that upon ZIKV infection, cells expressing CMPK2 have reduced E protein expression and significantly lower viral titers as compared to control." (PMID 37075076, 2023). "Cytidine/uridine monophosphate kinase 2 (CMPK2) is also a type I interferon stimulated gene that was previously shown to affect translation and restrict ZIKV infection." (PMID 39065267, 2024).
avian influenza (1 paper, 2023). Infection of domestic and wild fowl and other birds with influenza A virus. "Chicken CMPK2 (chCMPK2) was reported to have antiviral activity against Avian influenza and Newcastle disease virus infection in chicken fibroblasts." (PMID 37075076, 2023).
cervical cancer (1 paper, 2021). A primary or metastatic malignant neoplasm involving the cervix. "A previous study showed that CMPK2 mRNA was readily detectable in monocyte/macrophage differentiating cell lines, such as THP-1 cells, but not in HeLa cells, a human cervical cancer cell." (PMID 34705862, 2021).
chronic myeloid leukemia (1 paper, 2021). "Interestingly, NRIR is located close to the protein-coding gene CMPK2, which is overexpressed in chronic myeloid leukemia K-562 and lymphoblastic leukemia MOLT-4 cell lines, implicating a role in the pathophysiology of these diseases." (PMID 33531590, 2021).
dengue virus infection (1 paper, 2021). "The enzyme CMPK2 not only supplies deoxyribonucleotides for the synthesis of mitochondrial DNA (mtDNA) but it also possesses immunomodulatory and antiviral activities: CMPK2 was shown to limit dengue virus infection of murine and human cells in an IFN-dependent and IFN-independent manner." (PMID 34684219, 2021).
encephalitis (1 paper, 2023). An acute inflammatory process affecting the brain parenchyma. "We also examined CMPK2’s antiviral effect on KUNV infection, which in humans mostly causes a mild febrile illness although some individuals can develop encephalitis." (PMID 37075076, 2023). "Finally, we examined the effect of CMPK2 on a double-stranded human DNA virus, herpes simplex virus type 1 (HSV-1), belonging to the Herpesviridae family that causes a range of clinical symptoms from common cold-sores and fever blisters to encephalitis and neonatal disease involving multiple organs." (PMID 37075076, 2023).
Flavivirus Infections (1 paper, 2023). Infections with viruses of the genus FLAVIVIRUS, family FLAVIVIRIDAE. "We focus here on the scope of CMPK2’s antiviral activities and the functional characterization of CMPK2 in the context of flavivirus infection." (PMID 37075076, 2023).
glioblastoma (1 paper, 2025). The most malignant astrocytic tumor (WHO grade IV). "In this study, we aimed to evaluate the potential of boron supplementation (as BA) in inhibiting glioblastoma growth in a xenograft animal model, specifically assessing its role as a CMPK2 inhibitor, and contributing to the emerging interest in CMPK2 as a therapeutic target in GBM." (PMID 39821858, 2025).
HCMV infection (1 paper, 2023). "To validate the transcriptomic data, we performed quantitative real-time PCR (RT-qPCR) and immunoblot to analyze the effect of ectopically expressed UL23 on the expression of APOL1, CMPK2, and LGALS9 upon IFN-γ stimulation or HCMV infection." (PMID 37112994, 2023). "As expected, UL23 significantly restricted IFN-γ-induced gene expressions of APOL1, CMPK2, and LGALS9; UL23 also significantly reduced their expression during HCMV infection." (PMID 37112994, 2023).
mastitis (1 paper, 2025). Inflammation of breast tissue during lactation or postpartum due to an obstructed duct or infection. "The findings indicated that while Nia alleviated the symptoms of S. aureus‐induced mastitis and reduced the bacterial load in the mammary gland, this improvement was significantly reversed upon CMPK2 overexpression." (PMID 39792800, 2025). "Based on the previous findings, alterations in CMPK2 expression within mammary tissue were further investigated, revealing that Nia significantly inhibited the protein levels of CMPK2, cGAS/STING, and key executive proteins involved in PCDs in S. aureus‐induced mastitis in mice." (PMID 39792800, 2025).
respiratory syncytial virus infection (1 paper, 2025). "Cytidine/Uridine Monophosphate Kinase 2 (CMPK2) is an activator of the NLRP3 inflammasome that is differentially expressed in response to SARS-CoV-2, influenza virus, rhinovirus, and respiratory syncytial virus infection." (PMID 40778772, 2025).
Sepsis (1 paper, 2023). Sepsis is defined as life-threatening organ dysfunction caused by a dysregulated host response to infection. "Overall, the clinical data showed that higher levels of CMPK2 in sepsis patients were associated with triggering inflammation and excessive immune reactions." (PMID 37859535, 2023). "We used this strategy to identify a naturally sourced small molecule, DP, which inhibits NLRP3 inflammasome activation via CMPK2 and, thus, is a potential treatment for inflammasome‐associated diseases such as sepsis." (PMID 37859535, 2023). "Strikingly, DP significantly attenuated LPS‐induced sepsis in a mouse model, but its effect was weakened in mice with myeloid‐specific Cmpk2 ablation." (PMID 37859535, 2023). "In our recent work, we found that in the whole blood of sepsis patients, the CMPK2 gene is significantly overexpressed compared with that in healthy human volunteers." (PMID 37859535, 2023). "Strikingly, DP significantly attenuated LPS‐induced sepsis by restricting CMPK2, but its effect was weakened in Cmpk2∆DMye mice." (PMID 37859535, 2023). "Here, we found that the CMPK2 gene is highly expressed in the whole blood of sepsis patients by RNA‐Seq." (PMID 37859535, 2023). "Collectively, these findings reveal that DP is a promising CMPK2 inhibitor for the treatment of sepsis." (PMID 37859535, 2023). "Notably, by whole‐blood RNA‐seq, we found that the CMPK2 gene was dramatically upregulated in sepsis patients compared to healthy volunteers." (PMID 37859535, 2023). "To determine the primary function of the target protein CMPK2 in patients with sepsis, we collected clinical data of whole‐blood RNA‐seq from 348 patients with sepsis from four emergency departments and one intensive care unit, while matching 44 healthy volunteers as clinical controls." (PMID 37859535, 2023). "The discovery of CMPK2 spurred hopes for the treatment of sepsis." (PMID 37859535, 2023). "However, CMPK2‐untapped target inhibitors are still an enormous obstacle that has hindered the CMPK2‐centric treatment of sepsis." (PMID 37859535, 2023). "The CMPK2 gene is highly expressed in the whole blood of sepsis patients." (PMID 37859535, 2023).